FGF18 (fibroblast growth factor 18)
Diseases named in the same sentence as FGF18 in open-access papers (continued):
Sharing a sentence is not in itself a finding about the gene and the disease.
hepatocellular carcinoma (7 papers, 2012 to 2023). A malignant tumor that arises from hepatocytes. "Overexpression of FGF18 has been frequently identified in several neoplasms, including hepatocellular carcinoma, gastric cancer, and colon cancer." (PMID 33117668, 2020). "FGF8 and FGF10 are involved in embryonic liver development, FGF7 and FGF9 in repair in response to liver injury, and FGF5, FGF8, FGF9, FGF17, and FGF18 in the development and progression of hepatocellular carcinoma." (PMID 27148532, 2016). "In addition, FGF5, FGF8, FGF9, FGF17, and FGF18 play roles as paracrine signals in the development and progression of hepatocellular carcinoma." (PMID 27148532, 2016). "Recently, our group investigated the role of FGF8, FGF18, and FGFR4 in colo-(rectal) and hepatocellular cancer." (PMID 31527546, 2019). "In hepatocellular carcinoma, FGF8 subfamily members, including FGF8, FGF17 and FGF18, were upregulated to facilitate cell survival and angiogenesis via activating ERK." (PMID 30082912, 2019).
liver fibrosis (7 papers, 2022 to 2025). "We performed RNA-seq of the whole liver to elucidate the mechanisms underlying FGF18-induced liver fibrosis." (PMID 37813881, 2023). "To determine whether FGF18 attenuates or exacerbates liver fibrosis in CflarLKO mice, we generated hepatocyte-specific Fgf18-deficient mice (Fgf18LKO mice) by crossing albumin-Cre mice with Fgf18FF mice." (PMID 37813881, 2023). "The partial attenuating effect of Fgf18 deletion on liver fibrosis may be caused by residual expression of Fgf18 in HSCs or compensation by other cytokines." (PMID 37813881, 2023). "In this study, we identified OPN as a novel downstream effector of FGF18 in promoting liver fibrosis." (PMID 40678531, 2025). "We previously showed that fibroblast growth factor 18 (FGF18) promotes liver fibrosis by increasing HSC proliferation." (PMID 40678531, 2025). "Future studies evaluating the therapeutic potential of the dual inhibition of FGF18 and OPN—both in liver fibrosis and in cancers with elevated Fgf18 and Spp1 expression—are warranted." (PMID 40678531, 2025). "Compared with control mice, CflarLKO mice rapidly develop liver fibrosis fed a choline-deficient, ethionine-supplemented (CDE) diet, and FGF18 was identified as a novel factor that promotes liver fibrosis." (PMID 40678531, 2025). "Since FGF21 has been used to treat liver fibrosis by alleviating metabolic dysfunction, a comparison of its effects with those of FGF18 on HSCs and hepatocytes is of interest." (PMID 40678531, 2025). "Based on these data, we propose a model for how FGF18 promotes liver fibrosis in cooperation with TGFβ and OPN." (PMID 40678531, 2025). "Our previous study demonstrated that FGF18 plays a protective role in the liver, especially in liver fibrosis and hepatic ischemia-reperfusion." (PMID 38419044, 2024). "We identified FGF18 as a critical factor promoting liver fibrosis in murine chronic liver injury models." (PMID 37813881, 2023). "Deletion of Fgf18 in hepatocytes attenuated CDE-induced fibrosis in CflarLKO mice; conversely, overexpression of Fgf18 promoted liver fibrosis by increasing the number of HSCs." (PMID 37813881, 2023). "In the present study, we found that the expression of Fgf18 was elevated in various murine liver fibrosis models." (PMID 37813881, 2023). "From a therapeutic perspective, it would be intriguing to investigate the effect of shRNA-mediated deletion of Fgf18 in adult mice with liver fibrosis." (PMID 37813881, 2023). "Deletion of Fgf18 in hepatocytes attenuates liver fibrosis; conversely, overexpression of Fgf18 promotes liver fibrosis." (PMID 37813881, 2023). "Our previous study demonstrated that FGF18 protects against liver fibrosis by inhibiting activation of HSCs mediated by the Hippo signaling pathway." (PMID 37777507, 2023). "In addition, patents are pending in Japan to use the hepatocyte-specific Fgf18 Tg mice as an animal model of liver fibrosis." (PMID 40678531, 2025). "Given that FGF18 contributes to liver fibrosis by promoting HSC proliferation while mitigating TGF-β-induced profibrotic gene expression, we hypothesized that FGF18 might regulate additional target genes involved in liver fibrosis." (PMID 40678531, 2025). "Addressing these limitations in future studies will further elucidate the role of the FGF18-OPN axis in liver fibrosis and may contribute to the development of novel antifibrotic therapies." (PMID 40678531, 2025). "Given that FGF18 and TGFβ may cooperate to promote liver fibrosis under certain conditions, focusing on genes coinduced by both stimuli is reasonable." (PMID 40678531, 2025). "We propose the following model of how FGF18 promotes liver fibrosis." (PMID 37813881, 2023). "To determine whether our data obtained from murine experiments are relevant to human liver fibrosis, we examined the expression of FGF18 in liver biopsy samples to diagnose various human liver diseases." (PMID 37813881, 2023).
liver fibrosis (continued). "Our findings suggest that FGF18 promotes liver fibrosis and could serve as a therapeutic target to treat liver fibrosis." (PMID 37813881, 2023). "To determine whether the expression of FGF18 alone induces liver fibrosis in vivo, we generated transgenic mice expressing Fgf18 in hepatocytes." (PMID 37813881, 2023). "Intriguingly, the expression of Fgf18 was also elevated in choline-deficient, L-amino acid-defined, high-fat diet (CDAHFD)-induced murine MASH or 3,5-diethoxycarbonyl-1,4-dihydrocollidine–supplemented (DDC) diet-induced liver fibrosis models in wild-type mice." (PMID 37813881, 2023). "Notably, the hepatocyte-specific deletion of Fgf18 only partially attenuated CDE-induced liver fibrosis in CflarLKO mice, suggesting that simultaneous blockade of FGF18 and OPN may be more effective." (PMID 40678531, 2025). "Thus, proliferating HSCs induced by FGF18 further respond to profibrotic stimuli derived from scar-associated macrophages, such as platelet-derived growth factor (PDGF) and IL-1β53, ultimately contributing to the development of liver fibrosis." (PMID 37813881, 2023). "Thus, FGF18 is a critical growth factor that promotes liver fibrosis and may be a therapeutic target for treating liver fibrosis." (PMID 37813881, 2023). "Thus, FGF18 promotes liver fibrosis and could serve as a therapeutic target to treat liver fibrosis." (PMID 37813881, 2023). "This feed-forward interaction between FGF18 and OPN was further supported by in vivo data derived from murine liver fibrosis models." (PMID 40678531, 2025). "Together, our results suggest that FGF18 drives a feed-forward loop between quiescent and activated HSCs/myofibroblasts via OPN signaling, thereby accelerating liver fibrosis progression." (PMID 40678531, 2025). "Regarding the contribution of FGF18 in hepatocytes, deletion of Fgf18 in hepatocytes moderately attenuated CDE-induced liver fibrosis." (PMID 37813881, 2023). "To date, a variety of intracellular signaling pathways including acid ceramidase, fibroblast growth factor 18 and Hedgehog signaling pathways have been shown to act as a modulator of YAP1 activity, thereby altering HSC activation and liver fibrosis." (PMID 36091042, 2022). "Here, the authors show that FGF18 promotes liver fibrosis by stimulating hepatic stellate cell proliferation, without concomitant upregulation of profibrotic genes." (PMID 37813881, 2023). "GO enrichment analysis revealed that these overlapping genes were categorized in cell adhesion, extracellular matrix organization, and collagen fibril organization, suggesting that expression of Fgf18 alone upregulates, at least in part, signature genes involved in CDE-induced liver fibrosis." (PMID 37813881, 2023). "Notably, FGF18 overexpression alone induces liver fibrosis in vivo, suggesting that its profibrotic effects are not limited to promoting HSC proliferation." (PMID 40678531, 2025). "However, in the long term, FGF18 seems to stimulate HSC proliferation, and subsequently, the proliferating HSCs become responsive to subsequent profibrotic stimuli ultimately leading to liver fibrosis." (PMID 37813881, 2023). "The expression of Cd34 and the numbers of CD34+ cells were increased in the livers of CflarLKO mice fed the CDE diet and wild-type mice fed the CDAHFD diet, suggesting that the expansion of CD34+ cells is not specific to Fgf18 Tg mice but a more generalized phenomenon in liver fibrosis." (PMID 37813881, 2023). "Hence, it would be interesting to test whether liver fibrosis is attenuated in mice lacking Fgf18 in HSCs by crossing Fgf18flox/flox mice with Lrat-Cre Tg mice." (PMID 37813881, 2023).
serous ovarian cancer (6 papers, 2014 to 2025). "It has been demonstrated that FGF18 regulates both tumor cells and tumor microenvironment to facilitate the progression of serous ovarian cancer, enhancing angiogenesis and tumor-associated macrophage infiltration." (PMID 27259239, 2016). "FGF18 (Fibroblast Growth Factor 18) has been identified as an important prognostic and therapeutic biomarker in high-grade serous ovarian cancer." (PMID 40330466, 2025). "Tumor microvessel density (MVD) increased with FGF18 expression in serous ovarian cancer, and FGF18 and MVD increased significantly in type I to type II cancer progression." (PMID 37228502, 2023). "In addition, transcriptome sequencing analysis of a benign ovarian epithelial tumor cell line MCV152 and an ovarian serous cancer cell line SKOV-3 identified FGF18 as an up-regulated gene, which was validated in WB." (PMID 37228502, 2023).
colon cancer (5 papers, 2016 to 2023). "It has been reported that there is a positive association between FGF18 expression and development of some human cancers, including colon cancer[45 ▶]." (PMID 32429632, 2020). "One previous study showed that targeted disruption of β-catenin significantly blocked FGF18 expression, while another found that β-catenin is capable of enhancing FGF18 transcription in colon cancer from the promoter of FGF18 harboring TCF4-binding motifs." (PMID 35277183, 2022). "Interestingly, it has been observed that in slow proliferating colon cancer cell lines (like Caco-2 and LT-97), addition of FGF18 to the cell culture can elevate cell proliferation[45 ▶]." (PMID 32429632, 2020). "Our recent work confirmed that CD44-positive colorectal adenoma cell growth and survival depend on autocrine FGF18/FGFR3-IIIc signaling, thus indicating importance of this pathway already in precursor lesions of colon cancer." (PMID 27650542, 2016).
dyslexia (4 papers, 2014 to 2020). A learning disorder characterized by an impairment in processing written words. "However, it is worth noting that GWAS for dyslexia have been under‐powered so far and variants with the strongest association to dyslexia (e.g., in genes RBFOX2, ABCC13, ZNF385D, COL4A2 and FGF18) failed to survive genome‐wide statistical scrutiny." (PMID 30218584, 2018).
lung carcinoma (4 papers, 2023 to 2024). "Western blot was used to verify that the protein expression level of FGF18 was increased in lung cancer cells due to the overexpression of HDACs." (PMID 37228502, 2023). "Knockdown or overexpression of FGF18 in human non-small cell lung cancer cell A549 significantly reversed the effects of HDACs on the proliferation, migration and cell cycle of lung cancer cells." (PMID 37228502, 2023). "Regarding the prediction of differential expression and clinical relevance of FGF18 in lung cancer and normal lung tissues." (PMID 37228502, 2023). "In conclusion, FGF18 plays an important role in promoting the growth and tissue progression of lung cancer cells through FGFR1-ERK/p38 pathway." (PMID 37228502, 2023). "In terms of the mechanism and pathway of FGF18 on lung cancer progression." (PMID 37228502, 2023). "In terms of FGF18 on the progression of lung cancer cells and tissues." (PMID 37228502, 2023). "In addition, stimulation of human lung cancer cell line H460 with recombinant FGF18 protein significantly promoted the proliferation of H460 cells." (PMID 37228502, 2023). "suggesting that FGF18 may affect lung cancer progression through the FGFR1 pathway." (PMID 37228502, 2023). "A recent study on lung cancer also validated HDAC7 contributed to the proliferation of cancer cells by deacetylating β-catenin and further activating FGF18 expression." (PMID 36653340, 2023). "The interaction between FGF18 and FGFR in lung cancer progression was investigated." (PMID 37228502, 2023).
melanoma (4 papers, 2012 to 2024). A malignant, usually aggressive tumor composed of atypical, neoplastic melanocytes. "In conclusion, this study provides insight into the potential mechanisms underlying Si162 resistance in melanoma cells and identified 5 genes (CNTN6, ADD1, FGF18, C18orf25, and RPL13) as potential prognostic biomarkers for Si162 resistance." (PMID 38665777, 2024). "The expression of FGF18 in VM7, VM10, VM21, VM24 and other melanoma cell lines was less than that in NM, but the expression of FGF18 in VM23 and VM31 was more than that in NM." (PMID 37228502, 2023). "Interestingly, the expression of FGF18 in different melanoma cell lines was different." (PMID 37228502, 2023). "Expression of FGF18 and four FGFR genes was detected in 12 normal melanoma cell lines (NM) and melanoma cell lines by RT-PCR." (PMID 37228502, 2023). "Therefore, the role of FGF18 and FGFR in melanoma progression remains to be explored." (PMID 37228502, 2023).
cardiac hypertrophy (3 papers, 2021 to 2025). "The hierarchical cluster heatmap and Venn diagram indicated that 5 of 22 FGF genes (FGF1, FGF5, FGF12, FGF16, and FGF18) were associated with myocardial hypertrophy." (PMID 36871047, 2023). "By contrast, cardiomyocyte-specific FGF18 overexpression attenuated pathologic cardiac hypertrophy associated with decreased ROS accumulation." (PMID 36871047, 2023). "Overall, these results indicate that FGF18 might play a critical role in the regulation of cardiac hypertrophy, and was associated with oxidative stress." (PMID 36871047, 2023). "This study provides a mechanistic underpinning for clinical observations and indicates that FGF18 is a potential therapeutic factor or functional biomarker in the chronic phase of cardiac hypertrophy." (PMID 36871047, 2023). "FGF18 suppressed ROS accumulation by increasing the activity and expression of FYN under conditions of myocardial hypertrophy, suggesting that the protective effect of FGF18-FYN on cardiomyocytes is related to the suppression of ROS generation." (PMID 36871047, 2023). "Here we investigate the regulation and function of the FGF18 in pressure overload (PO)-induced pathological cardiac hypertrophy." (PMID 36871047, 2023). "Overall, these results suggest that FYN plays a critical role in protecting against cardiac hypertrophy as downstream of FGF18." (PMID 36871047, 2023). "Collectively, these data suggest that the interaction between FYN and NOX4 is essential for regulating FGF18 against myocardial hypertrophy." (PMID 36871047, 2023). "Collectively, these data indicate that FYN is involved in the protective effects of FGF18 against cardiac hypertrophy in vivo." (PMID 36871047, 2023). "In conclusion, the present study identified a previously unrecognized biological function of FGF18 in cardiac hypertrophy." (PMID 36871047, 2023). "We, therefore, used FGF18 heterozygous mice (Fgf18+/− mice) to evaluate the impact of FGF18 on cardiac hypertrophy." (PMID 36871047, 2023). "Similarly, FGF18 has been shown to protect against pressure overload-induced pathological cardiac hypertrophy, cardiomyocyte death, fibrosis, and dysfunction." (PMID 40585885, 2025). "Together, these data demonstrate that FGF18 is protective against cardiac hypertrophy in vitro." (PMID 36871047, 2023). "In the present study, we analyzed the role of FGF18 in pathologic cardiac hypertrophy." (PMID 36871047, 2023). "Although the role of FGFs in cardiovascular disease has attracted extensive attention, the potential role of FGF18 in pathological cardiac hypertrophy remains unknown." (PMID 36871047, 2023). "The FGF18 and FGF22 genes are known to play a role in heart development and physiological processes while the MYC gene is implicated in angiogenesis, cardiomyogenesis, apoptosis, oxidative stress response and plays a major role in initiating and maintaining cardiac hypertrophy and contractility." (PMID 33788842, 2021). "Taken together, these results suggested that FGF18 upregulates FYN activity, which in turn negatively regulates NOX4 activity and then prevents cardiac hypertrophy." (PMID 36871047, 2023). "We observed that mice lacking FGF18 (Fgf18+/−KO and Fgf18-CKO) were prone to developing cardiac hypertrophy under stress, and overexpression of FGF18 antagonized PO- or ISO-induced cardiac hypertrophy." (PMID 36871047, 2023). "Mechanistic studies indicate that FGF18/FGFR3 promote FYN activity and expression and negatively regulate NADPH oxidase 4 (NOX4), thereby inhibiting reactive oxygen species (ROS) generation and alleviating pathological cardiac hypertrophy." (PMID 36871047, 2023). "Despite the importance of FGF18 as a paracrine factor, no studies have focused on its role in pathologic cardiac hypertrophy." (PMID 36871047, 2023).
cardiac hypertrophy (continued). "Although the roles and mechanisms of FGF134, FGF535, FGF1236, and FGF1637 in myocardial injury have been revealed successively, the role of FGF18 in pathological myocardial hypertrophy has never been reported in detail." (PMID 36871047, 2023). "FGF18 heterozygous (Fgf18+/−) and inducible cardiomyocyte-specific FGF18 knockout (Fgf18-CKO) male mice exposed to transverse aortic constriction (TAC) demonstrate exacerbated pathological cardiac hypertrophy with increased oxidative stress, cardiomyocyte death, fibrosis, and dysfunction." (PMID 36871047, 2023). "This study uncovered the previously unknown cardioprotective effect of FGF18 mediated by the maintenance of redox homeostasis through the FYN/NOX4 signaling axis in male mice, suggesting a promising therapeutic target for the treatment of cardiac hypertrophy." (PMID 36871047, 2023). "Interestingly, AAV-mediated cardiac overexpression of FYN did not wholly rescue PO-induced cardiac hypertrophy in Fgf18-CKO mice, indicating that the full biological function of FYN is attributable to FGF18-regulated FYN quantification and activity." (PMID 36871047, 2023).
cleft lip (3 papers, 2016 to 2022). Congenital defect in the upper lip where the maxillary prominence fails to merge with the merged medial nasal prominences. "Moreover, genome-wide association studies of cleft lip and palate in humans have shown disease association with the FGF18 locus." (PMID 26745863, 2016). "Furthermore, Fgf9 and Fgf18 have overlapping functions in skeletal development and they have been shown to interact in families with cases of cleft lip and palate." (PMID 33959039, 2021). "Fgf18 and Wnt3a were associated with non-syndromic cleft lip with or without palate (NSCL/P)." (PMID 36685938, 2022).